FMOD (fibromodulin)
Diseases named in the same sentence as FMOD in open-access papers (continued):
Sharing a sentence is not in itself a finding about the gene and the disease.
tumor (continued). "Recently, it has been shown that FMOD, along with other SLRP family members, is not only implicated in cell adhesion and collagen fibrillogenesis, but also contributes to regulate the tumor growth suppression, transcription factors activity, and apoptosis prevention." (PMID 31198406, 2019). "FMOD has been known as one of TAA in B-CLL which is able to provide a specific anti-tumor response." (PMID 31198406, 2019). "Fibromodulin can therefore be a unique effector of dense collagen matrix assembly in tumor stroma and, without affecting other major matrix components or the cellular composition, can function as a main agent in tumor barrier function." (PMID 28827814, 2017). "Fibromodulin (FMOD), as an important component of the extracellular matrix, not only plays a role in structure, but also is regarded as a novel tumor-associated antigen for a variety of malignant tumors, including ULM, and has the potential as a biomarker for cancer diagnosis and treatment." (PMID 39640883, 2024). "However, our in vitro findings did not correlate with observations in xenograft models, where FMOD deficiency did not affect angiogenesis, as indicated by the comparable densities of tumor-associated endothelial structures." (PMID 35737114, 2022). "However, doxycycline treatment would inhibit FMOD expression, and thus one could investigate the importance of DGC-secreted FMOD in tumor growth." (PMID 35642785, 2022). "The results indicated that in GBM tumor tissue, OSMR and FMOD were primarily distributed in astrocytes, IGFBP6 in NPC, G0S2 in macrophages, and IGHG2 in T cells." (PMID 39815665, 2025). "Fibromodulin (FMOD), belonging to the family of small leucine-rich proteoglycans, plays a role in the regulation of tumor angiogenesis." (PMID 38331776, 2024). "RT-PCR results showed that the expression of FMOD, MXRA5 and RAB36 in tumor tissues of most patients was higher than that in paracancerous tissues." (PMID 39513108, 2024). "We determined gene expression in nine cancerous and tumor- adjacent tissues from patients with GBM and found that expression levels of FMOD, MXRA5, and RAB36 in the cancer tissue was higher than those in the para-cancerous tissue in most patients." (PMID 39513108, 2024). "Furthermore, we show that the interaction between tumor unmatched CAFs and HNSCC cells in the tumor spheroids is associated with significant changes in the mRNA expression of CAF-specific markers and a significant increase in FMOD and MMP9 expression in the 3D coculture model." (PMID 38822309, 2024). "To verify the oncogenic role of FMOD in driving OSCC progression in vivo, we established a xenograft OSCC tumor model by subcutaneous injection of CAL27-shFMOD-3 and CAL-27-shCON cells in nude mice and examined the growth of tumors." (PMID 37965134, 2023). "In all three tumor models (AGR53-GSCs, DBT-Luc-GSCs, and MGG8-GSCs), blood vessels formed by TDECs were significantly reduced in tumors formed in FMOD-silenced conditions." (PMID 35642785, 2022). "Our data reveal a novel mechanism linking FMOD to the activation of transcriptional co-factors YAP and TAZ, possibly via integrin/FAK signaling and crosstalk with the Hippo tumor suppressor pathway." (PMID 35737114, 2022). "FMOD is a secreted component of the ECM, a dynamic network of macromolecules that modulates interactions between tumor cells and stroma." (PMID 35737114, 2022). "Our in vitro data suggests that FMOD and SOX2 cooperation plays an important role in tumor vasculogenic mimicry." (PMID 35737114, 2022). "Despite the moderate staining of fibromodulin in LK0917 tumor spheroids, a relatively stronger staining was observed in tumor cell/CAF spheroids." (PMID 34283070, 2021). "According to the Expression Atlas, the hypoxia-associated molecules CALB1, DDAH1, GAP43 and GPR37, as well as the tumor markers ART3, ENOL2 and FMOD and the tumor promoter NTNG1, are typically expressed in hematopoietic stem cells." (PMID 32466393, 2020).
tumor (continued). "Proteome profiling identified characteristic tumor markers, including FSTL5, ART3, and FMOD, and revealed a strong prevalence of anti-inflammatory and tumor-promoting proteins characteristic for alternatively polarized myeloid cells in MB samples." (PMID 32466393, 2020). "The levels of eight hub genes expression (FN1, CCND1, CDH2, CXCL12, MET, IRS1, DCN and FMOD) in PTC and para-cancerous non-tumor tissues were detected by qRT-PCR." (PMID 32714651, 2020). "While not yet validated in BC, these findings support fibromodulin to be a potential therapeutic target to mitigate Wnt-driven tumour aggressiveness and metastasis." (PMID 41463344, 2025). "Furthermore, these two CAFs also significantly upregulated FMOD and MMP9 in LK0902 tumor cells compared to cocultures with their tumor-matched CAFs." (PMID 38822309, 2024). "Therefore, we further detected the expression levels of angiogenesis-related factors VEGF, FGF-2, FMOD, and PDGF-B in tumor tissues by qPCR." (PMID 38331776, 2024). "Interestingly, we found that both MMP9 and FMOD were upregulated in LK0902 and LK0923 cells when cultured with unmatched CAFs compared to when cultured with tumor-matched CAFs." (PMID 38822309, 2024). "Endostar combined with cisplatin might exert anti-tumor effects by down-regulating the expression of METTL3 and FMOD." (PMID 38331776, 2024). "The interaction between tumor unmatched CAFs and HNSCC cells in the tumor spheroids is associated with significant changes in the mRNA expression of CAF-specific markers and significant increases in FMOD and MMP9 in tumor cells compared to when cocultured with tumor-matched CAFs." (PMID 38822309, 2024). "Fibromodulin (FMOD) is the main proteoglycan that contributes to extracellular matrix (ECM) remodeling by binding to matrix molecules, thereby playing an essential role in tumor growth and metastasis." (PMID 36986805, 2023). "Our results suggested that RP4 promoted immune cells infiltration in lung metastasis sites by blocking FMOD function and further might inhibit the impact of TGF-βin tumor progress, which needs future study." (PMID 36986805, 2023). "The striking effects of dual FMOD and SOX2 silencing on metastasis suggest that FMOD-regulated tumor–host interactions might be coupled with SOX2-driven signaling mechanisms in our model." (PMID 35737114, 2022). "The presence of transcripts for FMOD, PRELP and OMD was widespread in the patients analyzed, while expression of LUM and KERA was detected in only around 50% of cases in both healthy and tumor tissue." (PMID 34440771, 2021). "Moreover, fibromodulin showed a moderate staining in LK0902 and LK1108 in tumor cell/CAF spheroids compared to tumor cell spheroids." (PMID 34283070, 2021). "Transcripts for the five genes encoding class II SLRPs (FMOD, LUM, PRELP, KERA and OMD) were quantified in both healthy and tumor tissue, with no significant expression differences between tissue type." (PMID 34440771, 2021). "Additionally, IRS1 (insulin receptor substrate 1), DCN (decorin), FMOD (fibromodulin), and CXCL12 (chemokine C-X-C motif ligand 12) were down-regulated in tumor tissues." (PMID 32714651, 2020). "FMOD is a main proteoglycan which contributes to remodeling of the ECM through binding to matrix molecules, thereby plays an essential role in tissue repair, tumor progression and cancer." (PMID 31198406, 2019). "COL2A1 and FMOD showed very similar expression patterns as ARG2 across sample groups defined by tissue and age status, demonstrating a higher expression level in the young tumor group than in the old tumor group." (PMID 28027300, 2016). "Though FMOD depletion significantly inhibited BrM, we hypothesized that FMOD is not functioning independently to drive the expansion of tumor foci into macrometastases." (PMID 35737114, 2022).
tumor (continued). "Analysis of a large genomic patient dataset revealed that the SLRPs lumican, fibromodulin and decorin as well as COL1A1 and COL6A1 all correlate with good overall survival in SHH MB patients; suggesting that the presence of this ECM shell in SHH tumours may be a reliable biomarker of good outcome." (PMID 36631900, 2023). "The significant alteration of proliferation and colony formation observed in vitro upon dual FMOD and SOX2 silencing, which contrasted the effects of single-gene depletion, suggests that FMOD and SOX2 functional roles might converge at the induction of tumor growth." (PMID 35737114, 2022). "Our results show a significantly higher mRNA expression of MMP1, MMP9, POSTN, GREM1, FMOD, and COL1A2 in tumor biopsies compared to normal tissue, but the significant difference between responder and non-responder groups was only found for the expression of FMOD mRNA." (PMID 34283070, 2021).
cancer (25 papers, 2012 to 2025). A tumor composed of atypical neoplastic, often pleomorphic cells that invade other tissues. "Beyond that, current evidence suggests that FMOD acts as diagnostic and prognostic biomarkers in cancers and exerts oncogenic roles by regulating cell apoptosis, angiogenesis, and migration." (PMID 37965134, 2023). "Elevated expression of FMOD has been associated with several types of cancer, and differential expression of FMOD has been observed in other pathophysiological conditions as well." (PMID 31824307, 2019). "In various cancers, the altered small leucine-rich proteoglycans (SLRPs) expression, such as decorin, biglycan, and FMOD, has been suggested as a diagnostic, prognostic and therapeutic tool." (PMID 31198406, 2019). "Here we report that although the collagen network architecture is changed, neither the quantitative or qualitative properties of glycosmaminoglycans are affected by fibromodulin-deficiency, in a syngeneic experimental model of carcinoma." (PMID 28827814, 2017). "Treatment of experimental carcinoma with an inhibitor of PDGF receptors, with prostaglandin E1 or growth of carcinoma in fibromodulin-deficient mice generate tumors that have an increased ECV and reduced IFP." (PMID 22479530, 2012). "FMOD has yet to be linked to VM but SOX2 was shown to facilitate VM of “stem-like” cancer cells." (PMID 35737114, 2022). "Besides different pre-clinical studies on FMOD, many clinical studies have highlighted the role of FMOD in cancer pathogenesis and its diagnostic roles." (PMID 31198406, 2019). "Taken together, these findings proposed that FMOD could be introduced as diagnostic and therapeutic biomarkers in treatment of various cancers." (PMID 31198406, 2019). "FMOD deficiency decreases interstitial fluid pressure and enhances extracellular volume in experimental carcinomas and results in declined collagen fibril thickness in experimental carcinoma." (PMID 31198406, 2019). "Our present data add to our previously published results, which show that fibromodulin-deficiency increases the extracellular fluid volume and lowers the interstitial fluid pressure in experimental carcinoma concomitant with a reduction of the collagen network density and collagen fibril thickness." (PMID 28827814, 2017). "Since the glycosaminoglycan content and quality is an important regulator of interstitial fluid volume we investigated whether fibromodulin deficiency not only affects the stromal collagen network but also affects glycosaminoglycans in experimental carcinoma." (PMID 28827814, 2017). "Based on these previous results we investigated whether fibromodulin deficiency decreased average collagen fibril thickness also in syngeneic OOC38 carcinoma grown in Fmod-/- C57BL6 mice." (PMID 28827814, 2017). "Since we previously have established that fibromodulin-deficiency alters hydraulic properties of experimental carcinoma it was important to investigate whether fibromodulin-deficiency alters the amount and composition of the HA and proteoglycan-rich ground substance." (PMID 28827814, 2017). "In experimental carcinoma, FMOD positively modulates collagen assembly to maintain a dense collagen scaffold and fluid balance, further protecting cancer cells from anti-cancer drugs." (PMID 36986805, 2023). "FMOD is utilized as a biomarker to be evaluated in clinical samples, and targeting FMOD can be developed as a useful therapeutic approach for cancer." (PMID 36986805, 2023). "Current evidences suggest that FMOD plays many roles in cancer development, including regulation of cancer cell apoptosis, promotion of angiogenesis and migration." (PMID 36986805, 2023). "Recent studies have shown that FMOD plays an vital role in the occurrence and development of malignant tumors." (PMID 37965134, 2023). "DCN, BGN, LUM and fibromodulin (FMOD) are the most reported members of SLRPs involved in cancer progression." (PMID 34888227, 2021).
cancer (continued). "Biglycan, lumican, and fibromodulin are overexpressed in various types of cancer, whilst decorin is overexpressed in some types of cancer and suppressed in others." (PMID 33202923, 2020). "Little was known about fibromodulin (FMOD) expression regulation and its role in cancer progression, or about the action targets and mechanisms of the anticancer benefits of Aspirin." (PMID 31824307, 2019). "Emerging evidence suggests that fibromodulin (FMOD), an extracellular matrix protein, is associated with cancer, and yet little is known about the regulation of FMOD expression and its role in cancer metastasis." (PMID 31824307, 2019). "Validation of FMOD transcript in a large population is required to ascertain its usefulness as a biomarker of cancer." (PMID 31198406, 2019). "FMOD is associated as a risk factor of poor GBM prognosis, while CCR5, as a cell surface receptor, plays a role in cancer cell proliferation, metastasis, and the formation of an immunosuppressive microenvironment." (PMID 29168083, 2018). "By its effects on collagen network assembly fibromodulin therefore constitutes a potential target for new treatments aimed to increase effectiveness of conventional anti-cancer treatment regimes." (PMID 28827814, 2017). "Fibromodulin-deficiency reduces IFP and increases ECV in experimental carcinoma and leads to decreased collagen fibril thickness in experimental carcinoma and in tail tendons." (PMID 28827814, 2017). "It is therefore possible to infer that fibromodulin-directed collagen network assembly can modulate the hydraulic properties of a carcinoma interstitium independently of glycosaminoglycans." (PMID 28827814, 2017). "The results showed that FMOD mRNA was abnormally expressed in most cancers." (PMID 37965134, 2023). "Moreover, FMOD is overexpressed in multiple cancers, including lung cancer, prostate cancer, and chronic lymphocytic leukemia, and is a potential biomarker for B-cell acute lymphoblastic leukemia." (PMID 36986805, 2023). "Overall, FMOD could be the next therapeutic target in cancer, and the molecules and signaling pathways regulating cancer progression involved in FMOD need further research." (PMID 36986805, 2023). "In order to further determine whether overexpression of FMOD transcripts is caused by miR-338, we further analyzed the expression of miR-338 in OSCC cancer and adjacent tissues." (PMID 37965134, 2023). "FMOD and SOX2 might both ensure cancer cell self-renewal capacity (stemness), a property linked to the induction of EMT and required for metastatic outgrowth." (PMID 35737114, 2022). "Current data suggest the important role of FMOD in the pathogenesis of cancer." (PMID 31198406, 2019). "It seems that more pre-clinical experiments and clinical studies (with large samples) could contribute to more understanding of FMOD roles in the cancer pathogenesis." (PMID 31198406, 2019). "FMOD acts through increasing the migration and angiogenesis to progress cancer." (PMID 31198406, 2019). "Thus Aspirin modulates the Wnt/β-catenin pathway, with HDAC6 as a direct target protein, and FMOD as a downstream transcriptional target gene in cancer metastasis, which reveals a significant link between regulation of FMOD with Aspirin action." (PMID 31824307, 2019). "The critical roles of FMOD in the pathogenesis of cancer had been ignored for a long time." (PMID 31198406, 2019). "Furthermore, expression of fibromodulin decreases in experimental carcinomas treated with a specific inhibitor of TGF-ß1 and -ß3, which correlates with decreased collagen fibril thickness." (PMID 28827814, 2017). "How FMOD expression is regulated, what role FMOD plays in cancer metastasis, how Aspirin exerts anticancer effects, and what mechanistic parts of the Wnt/β-catenin signaling pathway are involved remain as important outstanding issues in biology and cancer therapy." (PMID 31824307, 2019). "Hence, FMOD is potential candidate for cancer immunotherapy." (PMID 31198406, 2019).
cancer (continued). "In NFs, the significantly upregulated gene is fibromodulin (FMOD), an important ECM small leucine-rich proteoglycans protein, which plays a critical role in ECM organization and cancer pathogenesis." (PMID 36966276, 2023). "We then used the Ph.D.-12 phage display peptide library to obtain a novel FMOD antagonist peptide, named RP4, and tested its anti-cancer effects of RP4 in vitro and in vivo." (PMID 36986805, 2023). "In summary, we screened and identified a novel FMOD antagonist peptide, RP4, from a phage display library, and demonstrated its ability to suppress CRC progression by inhibiting cancer cell growth and metastasis." (PMID 36986805, 2023). "Hence, FMOD may additionally play a vital role in cancer diagnosis and treatment." (PMID 24603701, 2014). "In addition, recent experimental findings indicate that the pharmacological inhibition of fibromodulin with RP4 as an antagonist efficiently inhibits Wnt/β-catenin signalling, leading to a decrease in migration and invasion seen in cancer models." (PMID 41463344, 2025). "We find that FMOD activates ERK to promote BCCMI, which is reminiscent of hyaluronan mediated motility receptor (RHAMM) promoting BCCMI via activation of ERK, and undergoes the important part that ERK plays in cancer metastasis." (PMID 31824307, 2019). "Furthermore, other investigated cellular markers were not altered in carcinoma grown in mice of the two genotypes, suggesting that the role of fibromodulin in carcinoma may not be pivotal in aspects not related to collagen." (PMID 28827814, 2017).
heart disease (2 papers, 2020 to 2021). "Together with another group of four proteins from the SLRP family, namely fibromodulin (FMOD), osteomodulin (OMD), osteoglycin (OGN) and lumican (LUM), the importance of extracellular remodeling processes in heart disease is emphasized." (PMID 32670412, 2020).
kidney diseases (1 paper, 2025). "In kidney diseases, the expression pattern of FMOD is closely associated with the fibrosis process." (PMID 40825025, 2025).
FMOD also shares sentences with these, for which no sentence is quoted: infection (3 papers); lymphoma (3); Myocardial fibrosis (3); Obesity (3); diabetic nephropathy (2); endometriosis (2); small cell lung carcinoma (2); autism (1); brain disease (1); chronic kidney disease (1); connective tissue disorder (1); craniosynostosis (1); dilatation (1); disc degeneration (1); fibrosis (1); glaucoma (1); hematologic malignancies (1); immune system disease (1); joint disease (1); liver fibrosis (1); lupus erythematosus (1); nephrotic syndrome (1); rheumatoid arthritis (1); schizophrenia (1); triple-negative breast carcinoma (1); tuberculosis (1); type 2 diabetes mellitus (1).